TIMP3 (TIMP metallopeptidase inhibitor 3)
Diseases named in the same sentence as TIMP3 in open-access papers (continued):
Sharing a sentence is not in itself a finding about the gene and the disease.
cancer (continued). "Recent studies suggested that the expression of MMP-9 and TIMP3 could be modulated by miR-221 in other human cancer cells." (PMID 33730072, 2021). "In contrast, APC, DAPK1, IGSF4, RARB, and TIMP3 genes were found to be methylated in cancer cells." (PMID 34552632, 2021). "Since our study demonstrated higher expression of TIMP-2 in high-grade serous ovarian tumours, we used normal secretory Fallopian tube and cancer cell lines that expressed relatively more TIMP-2 than TIMP-1 or TIMP-3, to investigate in vitro the cellular functions of TIMP-2 by transient knockdown." (PMID 33023532, 2020). "TIMP3 protein was also measured in cancer and normal colon epithelial cells." (PMID 32171282, 2020). "Low expression of TIMP-3 leads to the increased activity of MMPs in cancer." (PMID 33419373, 2020). "Low TIMP‐3 expression has been associated with a poor prognosis and nodal metastasis in various cancers." (PMID 32744429, 2020). "Moreover, TIMP-3 restoration induces various types of cancer cells’ apoptosis and inhibits cell proliferation." (PMID 33126605, 2020). "Therefore, studies involving comprehensive mechanistic evaluation of the role of TIMP3 in different cancers and in different stages of same cancer are warranted." (PMID 30988064, 2019). "TIMP3 silencing is associated with the intensified ECM remodeling and cancer cell migration." (PMID 31921636, 2019). "This is surprising, since TIMP3 expression is frequently lost in several types of advanced cancers." (PMID 31671543, 2019). "Therefore, TIMP3 shows potential as a clinically relevant target for cancer treatment, which prompted us to further synthesize TIMP3 inducers as potential therapeutic agents against CRC." (PMID 31588243, 2019). "In contrast, TIMP3/4 expression levels are significantly lower in several types of cancer." (PMID 31882975, 2019). "It is reasonable to hypothesize here based on the findings of various studies that the role of TIMP3 can vary with different types of cancers and in different stages of same cancer." (PMID 30988064, 2019). "In order to determine whether MPT0B390 inhibited cancer cell growth through TIMP3 induction, we transiently transfected siRNA to decrease TIMP3 endogenous gene expression and the capability of survival rescue under MPT0B390 treatment was performed." (PMID 31588243, 2019). "It is therefore possible that TIMP3-1296T/C SNP induced probable up-regulation may contribute to increased supply of TIMP3 protein to counter possible increase in MMP activity which otherwise leads to various diseases including cancers." (PMID 30988064, 2019). "Methylation of TIMP-3 could cause TIMP-3 inactivation, and its inactivation is associated with cancer development in the kidney, brain, breast, colon, esophagus, gastric, head and neck, and lung cancer." (PMID 29467412, 2018). "Several sources of evidencesuggest that the induction of TIMP-3 may inhibit MMP-2and MMP-9 activity in cancer cells." (PMID 29633599, 2018). "We observed close correlation between aging and DNA methylation of RARβ2, CYB5R2 and TIMP3 suggesting that the prevalence of these methylation signals in these cancer-related genes could heighten the development of PCa in older AA men." (PMID 30204798, 2018). "KHSRP knockdown also inhibited the maturation of cancer-associated miRNAs, such as miR-21, miR-130b, and miR-301, and induced the expression of their target mRNAs, such as BMP6, PDCD4, and TIMP3, resulting in the inhibition of epithelial-to-mesenchymal transition." (PMID 29254151, 2017). "TIMP3 promoter methylation levels of CpG3, CpG4, CpG5 islands were altered in treated cancer cells." (PMID 28524540, 2017). "Methylation of the TIMP-3 gene promoter is the mechanism by which TIMP-3 is inactivated in cancer." (PMID 26075202, 2015). "In addition, accumulating evidence indicates that TIMP3 is frequently down-regulated in various types of cancer." (PMID 25226613, 2014).
cancer (continued). "Finally, Tissue Inhibitor of Metalloproteinases-3 (TIMP-3) has found to be silenced in several types of cancer by promoter gene hypermethylation, including CRC." (PMID 24643221, 2014). "All data suggest that the inhibitory effect of TIMP-3 in cancer development could identify TIMP-3 as a novel and useful biomarker in human cancer." (PMID 25171061, 2014). "Hence, the prognostic value of TIMP-3 in human cancers, including HCC, needs to be further elucidated." (PMID 25171061, 2014). "Additionally, a large number of clinical studies have evaluated TIMP-3 expression and its clinical significance in a variety of malignant tumors." (PMID 25171061, 2014). "In accordance with studies demonstrating an inhibitory effect of TIMP3 on the invasion of different invasive cancer cells, lentiviral overexpression of TIMP3 significantly inhibited the invasiveness of Cal78 cells, indicating the expression of functional active TIMP3." (PMID 23894681, 2013). "Unlike cancer-cell-associated TIMP-3, TIMP-3 expression within fibroblasts had no prognostic power (data not shown), nor was it associated with any clinicopathological factor." (PMID 17032447, 2006). "Moreover, in the present study we discovered a positive correlation between TIMP-3 protein within cancer cells and ER." (PMID 17032447, 2006). "This clearly identifies the potential of TIMP-3 for gene therapy of multiple cancer types." (PMID 10188875, 1999). "We have therefore sought to determine whether TIMP-3 can inhibit invasion and promote apoptosis in other cancer cell types." (PMID 10188875, 1999). "Thus, TIMP3 expression measurements in cancer patients could find applications in clinical assessments, offering valuable insights into disease assessment and prognosis forecasting." (PMID 41009435, 2025). "Therefore, the role of TIMP3 in cancer biology and progression needs to be elucidated." (PMID 38542164, 2024). "Moreover, TIMP3 might manifest as a tumor suppressor and its expression might be down-regulated in human cancer tissues." (PMID 36682035, 2023). "Furthermore, various novel studies have come across TIMP3 methylation in a myriad of cancers." (PMID 36061358, 2022). "However, the protein levels of MMP9, MMP12 and TIMP3 are increased in cancer cells." (PMID 32171282, 2020). "Therefore, TIMP3 may be exploited as a potential target for cancer treatment with various therapeutic benefits." (PMID 31588243, 2019). "However, in contrast to studies in human cancer cell lines or rat VSMCs, TIMP-3 induced apoptosis in hVSMCs is via a FAS-dependent type-I apoptotic pathway, as Bcl2 over expression did not inhibit apoptosis significantly and loss of mitochondrial membrane potential was not seen." (PMID 29617412, 2018). "Furthermore, it is interesting to note that upregulation of genes, such as ANKRD22, FRMD6, and KIR3DL2, and down-regulation of genes, such as TIMP3, SAP25, NAPSA, and TIMP are associated with a worse prognosis in cancer, are also associated with a worse prognosis in AdHF." (PMID 29236770, 2017). "The expression of TIMP-3 could be repressed by zeste homolog 2 and result in cancer cell migration." (PMID 25171061, 2014). "It is rational to presume that TIMP-3 could be used as a novel candidate for cancer therapy." (PMID 25171061, 2014). "In addition to MMP inhibition, TIMP3 blocks the binding of vascular endothelial growth factor (VEGF) to the VEGF receptor-2, causing inhibition of angiogenesis and has also been reported to induce apoptosis in cancer cells." (PMID 23527119, 2013). "Furthermore, changes in TIMP-3 were parallel to changes in certain genes responsible for apoptosis, which supports the notion that in cancer cells TIMP-3 may promote cell death by apoptosis." (PMID 21447156, 2011). "However, cancer-cell-associated TIMP-3 was not prognostic for disease-specific overall survival in the entire patient population or in any patient subset (data not shown)." (PMID 17032447, 2006).
cancer (continued). "This visualization highlights key genes (TIMP3, BRAF, and ITGB1, among the top 10 genes) that participate in multiple cancer-related and metabolic pathways, suggesting potential functional hubs and crosstalk among signaling networks." (PMID 41294900, 2025). "For instance, C2 expresses TIMP3, a metalloproteinase inhibitor that aids in the ECM remodeling, and NPNT, a gene reported to be related to development and cancer processes." (PMID 40111904, 2025). "Through integrative bioinformatic analysis of The Cancer Genome Atlas (TCGA) dataset and validation using the Loma Linda University (LLU) patient cohort, we demonstrated that ITGB1, TIMP3, and BRAF function as key molecular determinants of SOC prognosis." (PMID 41294900, 2025). "To verify the selected DEM (hsa-miR-21-5p), DEL (MIR99AHG) and 5 DEGs (RECK, TIMP3, EHD1, ERG and RASGRP1), we collected sequencing data from several cancer and normal tissues to explore the expression levels of these RNAs." (PMID 38495494, 2024). "Moreover, upregulated TIMP3 is associated with Thrombospondin 1 (THBS1) in the protein-protein interaction network, and upregulated TIMP3 may be involved in the ECM–receptor interaction signalling pathway during cancer metastasis." (PMID 38542164, 2024). "Thus, TIMP3 may be a key molecule in cancer cell dormancy and senescence." (PMID 38542164, 2024). "This is reasonable considering all genes are involved in related pathways such as Proteoglycans in cancer (ERBB2, TIMP3 and IGF2) and ECM–receptor interaction (COL6A2)." (PMID 38069080, 2023). "For cancer samples, the expression level was higher than in normal samples for DAPK1, MLH1 and MALAT1, and lower for MEG3, TIMP3 and SOX1." (PMID 35682732, 2022). "For cancer samples, DAPK1, MLH1 and MALAT1 had higher expression, and MEG3, TIMP3 and SOX1 had lower expression when compared to normal samples." (PMID 35682732, 2022). "TIMP-3 can inhibit the action of pro-MMP-2 that pertains to gelatinases, and is demonstrated to control cell death and suppress cancer cell invasion and metastasis 12-15." (PMID 35813301, 2022). "TIMP-3 is the only TIMP able to block both shedding mechanisms, thus regulating CD44 signalling in cancer progression." (PMID 35207132, 2022). "In the case of normal vs. cancer samples, significant differences were observed for the expression of MEG3, TIMP3 and MALAT1." (PMID 35682732, 2022). "Among them, TIMP3, the most common TIMP that is found in different types of cancer, is considered a marker of good prognosis because it prevents disease progression." (PMID 36612628, 2022). "In CCA, miR-21 promotes cancer cell proliferation by inhibiting the expression of programmed cell death 4 (PDCD4) and tissue inhibitor of metalloproteinase 3 (TIMP3) by targeting 15-PGDH/HPGD." (PMID 34299246, 2021). "The analysis of the TSG promoters‘ methylation level of standardized CpG islands in cancer tissue revealed significant decreases of ATM, PTEN, and TIMP3 genes after sumac treatment." (PMID 33375383, 2020). "Compared with control cells, mAb NJ001 altered downstream target genes matrix metallopeptidases 7 (MMP‐7) and tissue inhibitor of metalloproteinases 3 (TIMP‐3), both of which regulate cancer invasiveness and metastasis." (PMID 32744429, 2020). "We report the significance of CDKN2A hydroxymethylation by HPV status, as well as many other cancer-related genes, such as CDH1, TIMP3 and SFRP4." (PMID 33203436, 2020). "The inhibitory effect of MPT0B390 on cancer cell motility was slightly rescued in the TIMP3 knockdown stable clones, which indicated that MPT0B390 inhibited cancer cell migration through TIMP3 induction in vitro." (PMID 31588243, 2019). "In the AC subtype, there were also observed the positive correlations between TIMP3 in NLNT and MMP2 levels, both in cancer and NLNT (R = 0.699, p < 0.001, and R = 0.500, p = 0.021, respectively; rs)." (PMID 31921636, 2019).
cancer (continued). "As expected, reduced levels of TIMP3 and elastin (ELN), the major components of elastic fibers, were found in iCCA proteome profiles, while high levels of POSTN were found in all the cancer samples." (PMID 31687002, 2019). "On the other hand, the miR-21 up-regulation, which was found predominantly in patients with LNM associated with a decrease in tissue inhibitor of metalloproteinases 3 (TIMP3) protein, promoted ECM degradation and cancer cell invasion." (PMID 31683635, 2019). "Previous studies have reported that several genes are directly targeted by miR-191 in human cancers including TET1, TIMP3, SATB1, and DIECR1." (PMID 31153371, 2019). "FZD8, plasminogen activator, urokinase receptor, ITGA2, WNT2B, TIMP3, WNT5B, FGF5, heparanase, HBEGF and WNT3A were up-regulated in the proteoglycan pathways in cancer, whereas WNT10A, PIK3R3, IGF2 were down-regulated." (PMID 30482199, 2018). "miR-21 promotes migration of cancer cells by targeting Reversion Inducing Cysteine-Rich Protein with Kazal motifs (RECK), TIMP metallopeptidase inhibitor 3 (TIMP3), and T-Cell Lymphoma Invasion And Metastasis 1 (TIAM1) genes." (PMID 29491883, 2018). "Evaluating cancer tissue, CLOs demonstrated significant effects on methylation levels in RASSF1A and TIMP3 promoters." (PMID 28524540, 2017). "TIMP3 is a recognized regulator of TNF bioavailability, and TNF signaling has the capacity to either drive or suppress cancer progression." (PMID 25807548, 2015). "By targeting distinct molecules such as matrix metalloproteinase regulators TIMP3 and TIAM1, miR-21 plays an essential role in cancer progression and metastasis." (PMID 24039846, 2013). "TIMP3 mRNA levels were found to be ∼10–13-fold higher in the cancer cells treated with EZH2-specific shRNA (sh1) than control cells untreated with the shRNA, and as a result, TIMP3 protein levels were significantly increased by knockdown of EZH2 expression." (PMID 22272343, 2012). "With the combined use of the four methylation markers that exhibited differential methylation in cancer (APC, E-cadherin, hMLH1 and TIMP3), 33 (55%) patients had methylated serum DNA detected in at least one of these markers." (PMID 15942635, 2005). "The survival rates of patients with TIMP-3 (−) cancer were significantly lower than those of patients with TIMP-3 (+) and TIMP-3 (±) cancer (P=0.0003)." (PMID 15467768, 2004). "For instance, C2 expresses TIMP3, a metalloproteinase inhibitor that aids in the extracellular matrix remodeling, and NPNT, a gene reported to be related to development and cancer processes." (PMID 39005414, 2024). "Downregulation of the TIMP3 gene has been observed both in cancer tissue and in neighboring non-cancerous tissue and correlated negatively with miR-20a, which can point out the epigenetic silencing of the genes controlling the ECM remodeling." (PMID 36830984, 2023). "While properties of TIMP-3 in cancer have been extensively reviewed elsewhere, this review focuses on effects of TIMP-3 on ectodomain shedding that have functional consequences in cancer progression." (PMID 35207132, 2022). "Furthermore, the decreased TIMP3 leads to the enhanced epithelial to mesenchymal transition (EMT) process, thus promoting the cancer metastasis." (PMID 33560588, 2022). "Interestingly, other cancers such as lung, bladder, thyroid, breast, liver, or pancreas showed an overexpression of miR-221-3p where the tumor suppressor p57kip2, c-kit, PTEN TIMP3, and PUMA have been reported to be miR-221 targets." (PMID 31937854, 2020). "In conclusion, TIMP-3 may be an LADC-specific prognostic factor of NSCLC, and downregulation of TIMP-3 is critical for cancer progression." (PMID 33126605, 2020).
cancer (continued). "While TET1 was ectopically expressed by ~35-fold in the TET1-CD overexpression T24 cells, several previously identified TET1 target genes, such as TIMP3 and DKK1 in other cancer types, were also induced at 2.1- and 1.8-fold compared to the control cells (EV), respectively." (PMID 32528872, 2020). "Compared with the constant and opposing patterns of TIMP-1 and TIMP-3, variable trends have been reported for TIMP-2 and TIMP-4 in human cancer, which could due to the heterogeneity of the types and stages of cancer." (PMID 33419373, 2020). "We observed an inverse correlation between CDH13 methylation (p = 0.045; r = -0.21) and serum vitamin D level whereas TIMP3 methylation (p = 0.021; r = -0.24) and DRD2 methylation (p = 0.056; r = -0.201) showed inverse correlation with supplementary vitamin D in the cancer cases." (PMID 30204798, 2018). "As for TIMP-3, a large number of studies have shown that the expression of TIMP-3 was reduced in various cancer tissues when compared to non-cancerous tissues or in the advanced stages of cancer relative to the early stages of cancer." (PMID 25171061, 2014). "Targets of miR-21 in cancer include PTEN, PDCD4, LRRFIP1, RECK, TIMP-3, TPM1, BTG2, and Sprty2." (PMID 25366985, 2014). "It showed significantly higher frequencies of methylation of cancer-related genes (p14ARF, p15, p16INK4A, p73, TIMP3, E-cadherin, DAPK, and GSTP1) than EBV negative/ CIMP-H LLC, except for the methylation of hMLH1, and MGMT." (PMID 24188515, 2013). "Therefore, the transcriptional repression of TIMP2 and TIMP3 by EZH2 likely enhances ECM degradation and angiogenesis but reduces apoptotic activity, favoring cancer cell invasion and metastasis." (PMID 22272343, 2012). "Thus, TIMP3 and ADAMTS1 are genes classically correlated to invasion and the metastatic process, the main cancer attributes responsible for death." (PMID 19055846, 2008). "It has been suggested that the stabilisation of Fas by endogenous (TIMP-1 and TIMP-3) and synthetic MMP inhibitors is responsible for increased sensitivity to apoptosis of various cell types, including Dev neural precursors cells or cancer cells." (PMID 16316466, 2005). "In contrast, there was significantly decreased expression of MMP2 and MMP23, maspin, and the protease inhibitors tissue inhibitor of metalloproteinase 3 (TIMP3), TIMP4 and RECK (reversion-inducing cysteine-rich protein with Kazal motifs) in the cancer specimens." (PMID 15928670, 2005). "Aberrant methylation of TIMP-3 was demonstrated in primary cancers of the kidney, brain, colon, breast, and lung, but not in any of 41 normal tissue samples." (PMID 15467768, 2004). "Furthermore, the prognosis for patients with cancer that had lost TIMP-3 was significantly less favourable than that for patients with TIMP-3 (+) and TIMP-3 (±) cancer." (PMID 15467768, 2004). "miR-21 is not only upregulated in cRCC but is also involved in cancer progression (proliferation, migration, invasion, epithelial mesenchymal transition) and the cancer stem cell phenotype by targeting tumor suppressor genes such as PTEN, PDCD4, TIMP3 or LATS1." (PMID 36359921, 2022). "Overexpression of miR-103 has been found in several type human cancers and previous studies reported that miR-103 could enhance the proliferation, migration, and invasion of cancer cells by targeting anti-oncogenes DICER and PTEN, TIMP-3, PDCD10, KLF4 respectively." (PMID 28445396, 2017). "Furthermore, IHC analysis of an HCC TMA similarly showed a reduced cytoplasmic expression of TIMP-3 protein in cancer cells relative to normal non-cancerous cells." (PMID 25171061, 2014). "Tissue inhibitor of metalloproteinase-3 expression may be unfavourable for the survival of cancer cells, and cancer cells with a high grade of malignancy (more invasive and fewer apoptotic cells) may not express TIMP-3 for various reasons." (PMID 15467768, 2004).